INS (insulin)
Diseases named in the same sentence as INS in open-access papers (continued):
Sharing a sentence is not in itself a finding about the gene and the disease.
Hepatic steatosis (continued). "The HF was more detrimental in terms of insulin sensitivity, and it caused liver steatosis." (PMID 28638152, 2017). "In addition to its association with insulin function, hepatic steatosis is related to lipid metabolism, including lipolysis and lipogenesis." (PMID 28452943, 2017). "Furthermore, HO-1 deficiency was found to promote insulin sensitivity and reduce diet-induced fatty liver disease, which suggests a novel or additional role for HO-1 in the metabolic regulation of cellular signaling thresholds." (PMID 28445528, 2017). "Importantly, we observed that orchiectomy was associated with less liver steatosis and insulin sensitivity, despite cross-sex hormone treatment." (PMID 29159307, 2016). "Previous studies have suggested that physical inactivity is associated with fatty liver; hepatic fat accumulation is associated with insulin resistance in skeletal muscle; and insulin resistance in skeletal muscle may increase hepatic fat levels." (PMID 26938785, 2016). "In addition to its tight association with insulin function, hepatic steatosis is closely related to inflammation and is even defined as a chronic low-grade inflammatory response." (PMID 26882989, 2016). "Considering that previous studies have linked MUFA with reduced hepatic steatosis and improved insulin sensitivity, and PUFA (in particular omega-3) with improvements in LFTs, serum triglyceride (TG) and fasting blood glucose levels; dietary deficiencies in MUFA and PUFA are of concern." (PMID 26703719, 2015). "CCR2 deficiency also ameliorated hepatic steatosis and improved insulin sensitivity." (PMID 26136779, 2015). "Peripheral IR may cause fatty liver by elevating the plasma levels of FA, glucose, and insulin, which stimulates hepatic lipid synthesis and impairs hepatic β-oxidation." (PMID 26228038, 2015). "Previous studies conducted in Western countries demonstrated that the risk factors of fatty liver disease include age, gender, and metabolic factors, such as central obesity, higher BMI, elevated fasting blood glucose, insulin, TG, and cholesterol, and lower HDL levels." (PMID 25781622, 2015). "In contrast, serum levels of AIM may not be correlated with IR as assessed by HOMA-IR, but adipocytokines were associated with IR and insulin sensitivity, and serum levels of leptin were associated with hepatic steatosis." (PMID 24524410, 2014). "In conclusion, in the present phase 2, randomized double-blind controlled trial we show that TRC150094 did not improve insulin sensitivity and lipid metabolism or decrease hepatic steatosis in obese insulin resistant subjects with an increased cardiometabolic risk." (PMID 24586256, 2014). "Whether fatty liver per se increases the risk of cardiovascular disease or reflects liver systemic insulin resistance is unknown." (PMID 23924883, 2013). "Dysregulation of miRNA expression has been shown to influence glucose homeostasis, cholesterol metabolism and cause insulin resistence, which thus plays an important role in the pathogenesis of metabolic disorders such as T2D, atherosclerosis, fatty liver and Alzheimer’s disease." (PMID 24260478, 2013). "Although a high-fat diet may promote fat accumulation in the liver by simply providing more substrate for triglyceride synthesis, an important mechanism whereby a high-fat diet may drive hepatic steatosis is by causing selective insulin resistance." (PMID 22132342, 2012). "Increased insulin secretion has been directly implicated in the development of fatty liver disease." (PMID 22966224, 2012). "Therefore, treatment strategies for fatty liver disease, at present, are primarily focused on weight loss and use of insulin sensitizing agents." (PMID 21489294, 2011). "Thus, our analysis successfully recovered insulin signaling as a hallmark characteristic pathway involved in fatty liver disease." (PMID 22132232, 2011).
Hepatic steatosis (continued). "Subsequent studies in CCL2-deficient mice suggest that CCL2 plays a minimal role in glucose metabolism and insulin sensitivity in mice fed a normal diet, but is important for pathogenic macrophage infiltration into adipose tissue, insulin resistance, and hepatic steatosis induced by a high-fat diet." (PMID 20936118, 2010). "Long term, more prolonged insulin pulses may increase the risk of hepatic steatosis due to prolonged insulin action, as has been suggested." (PMID 20037650, 2009). "The improvement in insulin sensitivity observed in the almond group may facilitate more efficient lipid metabolism, potentially reducing hepatic de novo lipogenesis and the risk of hepatic steatosis." (PMID 38826341, 2024). "However, whether hepatic steatosis is a consequence or a cause of the metabolic derangements in insulin sensitivity is still debatable." (PMID 39337412, 2024). "The insulin-dependent regulation of hepatic glucose and lipid metabolism is essential for metabolic homeostasis, and as such, future investigation of the impact of Wdr23 loss on lipid metabolism and hepatic steatosis particularly on high-fat diets will be of great interest." (PMID 38767782, 2024). "For example, a body mass loss of 3–5% could decrease cardiovascular risk, a body mass loss of 2–5% lower the level of HbA1c in T2DM patients, and a body mass loss of 7–10% could improve insulin sensitivity, liver enzyme concentrations, and liver steatosis and fibrosis in obese NAFLD patients." (PMID 36386939, 2022). "Besides UDCA, several drugs including insulin resistance modifiers, antioxidants and weight loss agents have been studied and used clinically for the treatment of hepatic steatosis; however, there are concerns about the safety of these drugs and the side effects associated with long-term use10." (PMID 32332706, 2020). "Although it is unclear whether hepatic steatosis causes atherosclerosis directly through inflammation and reactive oxygen species, indirectly though insulin resistance-related processes, or both, the risk of atherosclerosis is higher with severe fatty liver than with simple steatosis." (PMID 29565984, 2018). "The hallmark of hepatic steatosis is triglyceride (TG) accumulation within hepatocytes caused by alterations in hepatic lipid metabolism changing the balance between the pathways of uptake, synthesis, degradation and secretion on a background of systemic insulin resistance." (PMID 23394097, 2013). "In HFD-fed mice, GGT attenuated body weight gain, improved glucose tolerance and insulin sensitivity, and alleviated hepatic steatosis and adipose hypertrophy, accompanied by suppression of lipogenic genes and induction of β-oxidation markers." (PMID 41836012, 2026). "These mice exhibited smaller adipocytes, reduced hepatic steatosis, and improved insulin signaling across key metabolic tissues." (PMID 41524084, 2026). "The liver plays a pivotal role in glucose and lipid metabolism, and the onset of T2DM is frequently associated with excessive lipid accumulation in the liver, resulting in hepatic steatosis and reduced insulin sensitivity." (PMID 41509193, 2026). "Batf3−/− mice developed aggravated hepatic steatosis, inflammation, and fibrosis, accompanied by enhanced adipose lipolysis, increased hepatic fatty acid uptake, and impaired insulin-AKT signaling." (PMID 42157937, 2026). "PHYLN-NIO markedly reduced body weight and body mass index, hepatic steatosis, and inflammation, while enhancing antioxidant status, insulin sensitivity, and lipid profiles." (PMID 42045980, 2026). "This transcriptional program is a major driver of elevated FA and TG synthesis in insulin-resistant states 2,12,13, subsequently leading to hepatic steatosis, increased VLDL secretion, and hypertriglyceridemia 13,19–24." (PMID 41509451, 2026). "Anthropometric data, biochemical parameters, hepatic steatosis grade, and insulin sensitivity indices (eGDR) were collected." (PMID 41597132, 2026).
Hepatic steatosis (continued). "In vivo, oral administration of L. crispatus (108 CFU) daily for 2 weeks followed by twice-weekly for 12 weeks significantly reduced hepatic steatosis, improved insulin sensitivity and cardiac function in a diet-induced cardiometabolic disorder mouse model." (PMID 41486160, 2026). "Metabolic dysfunction associated fatty liver disease (MAFLD) is a rapidly growing global health burden characterized by hepatic lipid accumulation, insulin resistance, oxidative stress, and inflammation." (PMID 42045980, 2026). "It is anticipated that this will improve insulin sensitivity and reduce fatty liver disease, hyperglycaemia and salt-sensitive hypertension." (PMID 41174263, 2026). "Studies have confirmed the efficacy of polyphenol-rich foods (naringenin, resveratrol, chlorogenic acid, etc.)and polyprenol-based formulations in reducing body weight and liver steatosis, improving biochemical markers and insulin resistance." (PMID 41011683, 2025). "FFDZ reduced body weight, liver weight, and levels of inflammatory cytokines, and it ameliorated hepatic steatosis, serum lipid profiles, insulin sensitivity, and glucose tolerance in mice with HFD-induced NAFLD." (PMID 40144651, 2025). "DNA methylation affecting the hepatic expression of dipeptidyl peptidase 4 (DPP4) can worsen the development of liver steatosis affecting hepatic insulin signalling and decreasing GLP‐1 levels." (PMID 40371883, 2025). "These include improvements in insulin sensitivity, reductions in hepatic steatosis, and attenuation of inflammation, highlighting their therapeutic potential for metabolic and neurodegenerative disorders." (PMID 40001526, 2025). "Insulin therapy has a positive impact by reducing hepatic steatosis and liver enzyme levels in patients with MASLD." (PMID 41155837, 2025). "Luteolin significantly reduced blood pressure, fasting blood glucose levels, serum insulin concentrations, free fatty acid levels, cholesterol levels, and hepatic steatosis." (PMID 41573724, 2025). "Responders at 12 months exhibited elevated BMI, waist circumference, hepatic steatosis indices, fat mass, and insulin levels at baseline, along with reduced muscle-to-fat and muscle-to-visceral adipose tissue ratios." (PMID 41079186, 2025). "We demonstrated that fatty liver induced by an HFD was alleviated with luteolin; the underlying processes appear to be its influence on increased insulin sensitivity and oxidative capacity." (PMID 40332475, 2025). "Arachidonic acid is a pro‐inflammatory omega‐6 fatty acid and a precursor to eicosanoids that promote inflammation and insulin resistance—key drivers of hepatic steatosis disease progression." (PMID 41170010, 2025). "This is of importance, as IP metabolism has been implicated in both the primary characteristics of MASLD/MASH, including hepatic steatosis and inflammation, as well as the secondary characteristics, such as hepatic insulin sensitivity." (PMID 41032702, 2025). "FGF21 and its analogues increase insulin sensitivity, reduce hepatic steatosis, and have antifibrotic activity, and thus are excellent drug candidates in MASLD." (PMID 41356370, 2025). "Despite these improvements, hepatic steatosis, hepatic insulin resistance, and the expression of genes related to lipid metabolism and glucose output remained unaltered." (PMID 40906363, 2025). "Compared to C10‐WT mice, long‐term HFD‐fed ATC10‐KO mice displayed improved glucose and insulin tolerance and attenuated hepatic steatosis." (PMID 39985288, 2025). "This process, known as hepatic de novo lipogenesis, generates toxic metabolites like glycerol and ceramides, perpetuating insulin resistance and creating a cycle that exacerbates hepatic steatosis." (PMID 39860434, 2025). "In the liver, PYY administration has been associated with decreased hepatic steatosis and downregulation of gluconeogenic enzymes (e.g., PEPCK and G6Pase), indicating potential enhancements in hepatic insulin responsiveness." (PMID 41228539, 2025).
Hepatic steatosis (continued). "RNF186 is a RING ubiquitin ligase that induces ER stress in hepatocytes, impairing insulin sensitivity, and inducing hepatic steatosis." (PMID 40292292, 2025). "This aligns with studies suggesting that hepatic steatosis more severely impacts glucose metabolism in women due to estrogen’s modulation of hepatic insulin sensitivity." (PMID 40691629, 2025). "Pioglitazone, a thiazolidinedione class insulin sensitizer, improves hepatic steatosis, lipid metabolism, and insulin sensitivity in NAFLD patients." (PMID 41515160, 2025). "Metabolic agents such as GLP-1 receptor agonists (liraglutide, semaglutide) and THR-β agonists (resmetirom) are now front-line options due to their ability to improve insulin sensitivity, reduce hepatic steatosis, and achieve histologic resolution." (PMID 40951083, 2025). "1-month-old Tfap2aΔHep mice showed tolerance to glucose and resistance to insulin, and 3- and 6-month-old mice developed hepatic steatosis and lipid accumulation in the liver." (PMID 40180937, 2025). "ANGPTL8 levels correlate positively with insulin resistance and triglyceride levels which are both key contributors to hepatic steatosis and steatohepatitis progression." (PMID 40276549, 2025). "Insulin sensitizers, particularly metformin and pioglitazone, are most effective in individuals with obesity‐driven IR, hepatic steatosis, or lipotoxicity." (PMID 40673471, 2025). "Uric acid was observed to directly impede insulin signaling, fostering insulin resistance, thus implicating it as a fundamental mechanism in the development of hepatic steatosis." (PMID 40283451, 2025). "On the other hand, hepatic PTEN knockout mice show enhanced PI3K/Akt signalling and hepatic insulin action, highlighting a dis-connect between hepatic steatosis and insulin action in the liver." (PMID 41032702, 2025). "Together, these mechanisms contribute to systemic insulin resistance, hepatic steatosis, inflammation, and fibrosis." (PMID 41334445, 2025). "This had a good effect in P3, P5, and P7 with a decrease in serum insulin levels and reversal of liver steatosis in P3." (PMID 40590205, 2025). "Fructose-rich diets, prevalent in soft drinks and sweetened beverages, particularly exacerbate hepatic steatosis by enhancing lipogenesis and insulin resistance, thus intensifying MASLD severity." (PMID 41001122, 2025). "In a randomized controlled trial of 12 weeks (n = 259), a Mediterranean diet reduced hepatic steatosis by 39% and improved insulin sensitivity." (PMID 41228562, 2025). "Results indicated that A. muciniphila reduced body weight, hepatic steatosis, and serum lipid levels, while improving insulin sensitivity and decreasing liver enzyme levels (ALT, AST)." (PMID 41257640, 2025). "Experimental studies have shown that the overexpression of 11β-HSD1 exacerbates hepatic steatosis, while the pharmacological inhibition of this enzyme improves insulin sensitivity and reduces the hepatic triglyceride content." (PMID 40729034, 2025). "Unsaturated FAs and derivatives provided by the diet, de novo lipogenesis, and triglyceride lipolysis are natural PPAR ligands that enhance insulin sensitivity and reduce hepatic steatosis and lipogenesis." (PMID 40673471, 2025). "The results demonstrated that both low and high doses of PRE effectively alleviated symptoms of MetS induced by HFD, including reducing the severity of hepatic steatosis, lowering lipid levels, and improving insulin sensitivity." (PMID 40552158, 2025). "Conversely, CHE weakly impacted insulin sensitivity and lipid metabolism despite also lowering hepatic steatosis." (PMID 40507838, 2025). "Extra virgin olive oil, a key component of the Med diet enhances fatty acid oxidation, inhibits lipogenesis, improves insulin sensitivity, and attenuates hepatic steatosis owing to its high MUFA content and antioxidant capacity." (PMID 41051618, 2025).
Hepatic steatosis (continued). "Mechanistically, these benefits stem from reductions in insulin resistance, visceral adiposity, and systemic inflammation, all of which are key contributors to hepatic steatosis and fibrosis." (PMID 41358327, 2025). "The synergistic potential of combining exercise with polyphenol supplementation was also highlighted, with several studies reporting additive or even multiplicative effects in improving lipid profiles, insulin sensitivity, and reducing hepatic steatosis." (PMID 40672421, 2025). "GLP-1 receptor agonists have demonstrated significant reductions in hepatic steatosis, largely attributed to improvements in insulin sensitivity and decreased de novo lipogenesis." (PMID 40243565, 2025). "The TXA2/TP pathway has been found to be a potential therapeutic target to enhance insulin sensitivity and to prevent hepatic steatosis and inflammation in MASLD patients." (PMID 41220583, 2025). "The whole body Grk5 KO mice exhibit impaired insulin signaling, which contributes to severe hepatic steatosis." (PMID 40666930, 2025). "Our results align with earlier observations showing that markers of metabolic dysfunction, including triglycerides, insulin, and liver enzymes, correlate positively with hepatic steatosis and negatively with HDL cholesterol." (PMID 40943248, 2025). "In obese mice, BAM15 decreased hepatic steatosis, reduced proinflammatory lipid intermediates, improved insulin sensitivity (confirmed via hyperinsulinemic-euglycemic clamps), and preserved lean mass and core body temperature." (PMID 40869061, 2025). "Our findings indicate that HIIT demonstrated more pronounced improvements in insulin sensitivity, hepatic steatosis and BAT structure, whereas MICT is more effective in reducing WAT weight and improving WAT structure." (PMID 40305497, 2025). "Collectively, our findings suggest that GP administration improves insulin signaling, hepatic steatosis, and inflammation, supporting its potential as a therapeutic agent for metabolic liver diseases." (PMID 40869401, 2025). "Liver-specific ATGL overexpression decreases hepatic steatosis and slightly improves liver insulin sensitivity, and hepatic ATGL expression is positively associated with fatty acid β-oxidation." (PMID 41465302, 2025). "An increased intake of omega-3 PUFA leads to a reduction in hepatic steatosis, an improvement in insulin sensitivity, and a reduction in inflammatory markers." (PMID 40426854, 2025). "Blocking TGF-β signaling genetically (SMAD3−/−) and pharmacologically (anti-TGF-β antibody, 1D11) in mice lead to protective effects: decreased body weight gain and fat mass, improved insulin sensitivity, ameliorated hepatic steatosis." (PMID 40301996, 2025). "In terms of replacing these dietary triggers, replacement of SFA with MUFA or PUFA has demonstrated benefits for hepatic steatosis, insulin sensitivity, and lipid profiles." (PMID 39842721, 2025). "On the contrary, pharmaceutical activation of Akt alleviated ethanol-induced fatty liver in mice, highlighting the metabolic link between insulin signaling and ALD." (PMID 41465598, 2025). "In animal models, treatment with the FXR agonist GW4064 alleviates diet-induced weight gain, prevents hepatic steatosis, and improves insulin sensitivity." (PMID 41438090, 2025). "Identifying SVO therapeutic interventions, such as resistance training, protein-optimized nutrition, and insulin-sensitizing therapies—strategies shown to reverse both sarcopenia and hepatic steatosis." (PMID 41117924, 2025). "Low-dose of clenbuterol enhanced basal in vivo glucose absorption in skeletal muscle and enhanced whole-body insulin sensitivity as well as reduced hepatic steatosis under chronic stimulation of diet-induced obesity (DIO) in mice." (PMID 39794453, 2025). "In hepatic steatosis, IR manifests as decreased insulin sensitivity in the skeletal muscle, liver, and adipose tissue." (PMID 40640818, 2025).